CD4 (CD4 molecule)
Diseases named in the same sentence as CD4 in open-access papers (continued):
Sharing a sentence is not in itself a finding about the gene and the disease.
infection (continued). "We further compared the changes in the levels of TNF-R1 and TNF-R2 gene transcripts, ascertained herein by p55 and P75 gene expression respectively, in each CD4/CD8-defined subpopulation obtained from thymuses of control or infected animals (14 days post-infection)." (PMID 22461911, 2012). "In addition, the median CD4 cell count was significantly higher in this group (595.0 cells/μL) suggesting possible recent infection, as compared to HIV-infected respondents who also reported that they were positive (412.0 cells/μL, p<0.0001)." (PMID 22574226, 2012). "In contrast, HIV-specific CD8+ T-cells express low levels of CCR6 and CCR4 and thus may be impaired in their ability to colocalize and control viral replication in CCR6+CCR4+ CD4+ T-cells, such as Th17 cells which are highly permissive to infection." (PMID 22470433, 2012). "Treatment with anti-CD4 results in higher fecundity of female worms in a primary infection and transfer of the effector T-cell subset from chronically infected animals significantly reduced worm burdens when transferred to naive mice before infection." (PMID 23053394, 2012). "Similar to CD4+ lymphocytes, this subpopulation only weakly responded to the infection at 4 DPI." (PMID 22384225, 2012). "This is consistent with our observation that patients dying of causes not related to infection had higher CD4 count and haemoglobin at the time of death compared to those dying of infection(s), and were also more likely to be virologically suppressed." (PMID 22905264, 2012). "Moreover, we have previously detected S100A7 in tonsillar epithelium and lymphocytes (CD19+, CD4+ and CD8+ cells) and found reduced levels in tonsils in response to infection and atopic predisposition." (PMID 22230654, 2012). "At the transcriptional level, only CD4+ cDCs from infected mice showed any significant increase in accumulation of Tgfβ mRNA and in no population of cDC did we observe any accumulation of Ido mRNA as a result of infection." (PMID 22911108, 2012). "A progressive thymic atrophy characterized by a diminution in the organ size linked to a marked depletion of CD4+CD8+ thymocytes (data not shown) was seen along with infection in C57BL/6 infected mice, thus confirming previous results." (PMID 22461911, 2012). "To determine the frequency of activation of antigen-specific CD4+effector T cells in the lungs early in infection, we adoptively transferredP25TCRTh1 cells on day 18 and harvested them on day 21 after infection ofwild-type mice with wild-type M. tuberculosis H37Rv." (PMID 21637811, 2011). "Our results demonstrated that there was no production of infectious virus in this in vitro model of HIV latency, and that the block to productive infection and response to activating stimuli closely mimic findings from latently infected CD4+ T-cells from patients on cART." (PMID 21992606, 2011). "While not essential for infection, this integrin is expressed on a subset of highly susceptible CD4 T cells that express high levels of CCR5 and low levels of CXCR4 and are concentrated in intestinal and, to a lesser extent, cervical mucosa." (PMID 21284905, 2011). "Ex vivo production of IFN-γ (intracellular staining) was determined in both non-stimulated and anti-CD3 mAb-stimulated cell cultures, which revealed effector cells induced during the acute infection and the total potential of CD4+ cells to secrete IFN-γ, respectively." (PMID 21814579, 2011). "Even though themechanism by which HIV replication disables the immune system is still unclear,measurements of the patient's CD4+ T cell counts and plasmaviral load have long been the benchmarks of immunologic assessment of diseaseprogression and staging of infection." (PMID 21602924, 2011). "Previous infections with this chimera resulted in a rebound in CD4 levels compared to controls." (PMID 21887365, 2011). "In addition, immature DCs and LCs express low levels of cell surface CD4 and CCR5 and are susceptible to infection with HIV." (PMID 22163292, 2011).
infection (continued). "Moreover, efficient infection of macrophages in vitro correlates with increased CD4 affinity, the capacity to use low CD4 levels, and with increased sensitivity to sCD4." (PMID 21760891, 2011). "These “inflammatory DC” may play a role in antigen presentation to CD4+ T cells that migrate to the site of infection at later time points." (PMID 22102816, 2011). "TheSIV/SHIV infection of rhesus macaques is the leading animal model of choice by manybecause it recapitulates many of the features of HIV infection and disease inhumans, including CD4+ T cells depletion and the slew ofopportunistic infections and malignancies." (PMID 21602924, 2011). "Data from this study shows that DC-SIGN may significantly contribute to cis infection by decreasing the dissociation of CD4, thereby promoting formation of the complex with gp120 leading to more rapid co-receptor binding and fusion." (PMID 22163292, 2011). "However, the animals with less than 3.3% of baseline CD4 T cells in the acute phase were approximately 20% more depleted late in the infection than expected based on constant level of virus control." (PMID 21359149, 2011). "Of note, such variants may first appear during the asymptomatic phase of infection, before AIDS is diagnosed, albeit after an initial decline of CD4+ T cells." (PMID 21284904, 2011). "Several studies have shown that HIV-infected CD4+ T cells also present viral epitopes that are recognized by CTLs before the productive stage of infection, i.e., during the intracellular eclipse phase before the infected cell starts to produce new viral particles." (PMID 21326882, 2011). "Throughout secondary infection, all CD4+ T cells in the spleen were CD11ahi." (PMID 21647373, 2011). "Therefore we concluded that the mechanism of CD4+ T cell destruction during acute SIVagm infection of RMs was through both direct viral lysis and bystander apoptosis, being similar to that reported for pathogenic SIVmac-infected RMs." (PMID 21829366, 2011). "This is consistent with the proposal that DC-SIGN may promote infection of immature dendritic cells by both concentrating virus at the cell surface and promoting binding to CD4." (PMID 22163292, 2011). "Whether this specificity contributes to infection control because it is expressed by direct antibody generation or, alternatively, by CD4 T cell help remains to be determined." (PMID 21980500, 2011). "Neutralization antibodies to HSV-2 (B cellular immunity) play a prominent role in prophylactic protection from infection in animal models, while CD4+ T cell-based cellular immunity to HSV-2 may play an important role in controlling recurrent human disease." (PMID 21575169, 2011). "Since about two-thirds of the recovered CD11c+ cells were MHC class II+ and <1% of Gr-1+ cells were class II+ (not shown), these data suggest CD11c+ lung dendritic cells are likely capable of presenting viral antigens to local CD4+ T cells during the early stage of secondary infection." (PMID 21647373, 2011). "In women, CD4+ T cells are indeed recruited to the cervix during active infection; however, CD8+ and dentritic cells are also recruited, and the relative proportions of these cells may be situational." (PMID 21747646, 2011). "As thymic dendritic cells (DC) are permissive to infection by HIV-1, we examined the ability of thymic DC to enhance infection of thymocytes which may contribute to the overall depletion of CD4+ T cells." (PMID 21639903, 2011). "While the lifetime risk of developing active TB is approximately 10% for immune-competent persons following initial infection, for persons with HIV coinfection the annual risk can exceed 10%, and the risk of TB reactivation rises as the CD4 cell count declines." (PMID 21234380, 2011). "Infection of cells by human immunodeficiency virus type 1 (HIV-1) is a multistep process beginning with the sequential binding of the gp120 subunit of the viral envelope glycoprotein (Env) to CD4 and a coreceptor CCR5 or CXCR4." (PMID 22145853, 2011).
infection (continued). "Overexpression of cathepsin B attenuated the CD4-independent vector infection in 293T cells." (PMID 21541353, 2011). "However, we found that CD4+CD25+FoxP3+ Treg cells are rapidly induced in the periphery during acute FIV infection." (PMID 21364928, 2011). "However, it should be noted that the EC50 for gnidimacrin against NL4-3 infection is 31 pM; gnidimacrin at 50 pM only down regulated CD4 and CXCR4 by approximately 25%." (PMID 22039528, 2011). "Although replicative infection in DCs and LCs is much less efficient than in CD4+ T cells and macrophages, infected DCs and LCs can efficiently release de novo synthesized virus particles to CD4+ T cells at the points of cell contact termed virological synapses." (PMID 22163292, 2011). "The death rate of infected CD4+ T cells could be estimated following depletion of uninfected cells locally, at around 28 days post-infection, and found to be approximately (half-life days)." (PMID 22125483, 2011). "The 2.4-fold increase in sCD4 sensitivity of the w4 viruses correlated with a corresponding fold increase in sgp120 binding to CD4-Ig and with enhanced infection of RC49 cells and primary macrophages, but this association dissipated at w7, two weeks prior to the first switch event in this animal." (PMID 21760891, 2011). "Expansion of these CD4+ T cells was proportional to the dose of GAS-2W used for infection." (PMID 21966268, 2011). "In addition, by concentrating virus at the DC cell surface, DC-SIGN increases the likelihood of interaction in cis with DC cell surface CD4 and co-receptor as suggested previously leading to infection in cis." (PMID 22163292, 2011). "However, a recent study by CASCADE cohort investigators found that nearly 30% of their patients had ≤ 500 CD4 cells/mm3 12 months after infection." (PMID 21831310, 2011). "Productive infection of CD4 T cells mainly occurs through fusion at the plasma membrane." (PMID 21994805, 2011). "The first phase largely consists of CD4+ T cells present in the airways at the time of infection." (PMID 21647373, 2011). "However, we also discovered that LIGHT-LTβR interactions suppress anti-parasitic immunity in the liver in the first 7 days of infection by mechanisms that restrict both CD4+ T cell function and TNF-dependent microbicidal mechanisms." (PMID 21998581, 2011). "The difference betweentransferred and endogenous cell responses on day 14 is consistent with ourprevious observation that initiation of adaptive immunity to M.tuberculosis is delayed until day 11–14 post-infection, andconsequently, endogenous CD4+ effector T cells specific forM." (PMID 21637811, 2011). "A study in Myd88-/- mice infected with L. major has highlighted the importance of TLRs, IL-1 and/or IL-18 in the induction of IL-12 and the generation of Th1 responses; MyD88 deficiency also resulted in complete abrogation of IFNγ production by CD4+ T cells and an inability to control infection." (PMID 21253574, 2011). "CD4-derived IL-2 could also help NKor CD8 T cells to clear parasites as has been shown in blood-stage infection." (PMID 21556142, 2011). "On day 8 and 11 after infection CD4+ T cell function was analyzed in spleen." (PMID 21966366, 2011). "We compared the effects of soluble DC-SIGN or soluble Langerin on HIV infection in vitro as a means of addressing whether the increased stability of the CD4:gp120 complex contributes to DC-SIGN enhancement of trans infection." (PMID 22163292, 2011). "Here, we show that chronic Plasmodium chabaudi malaria infection in mice enhances the expansion of CD4+ T cells in a second infection, and that this correlates with increased expression of the IL-2/15 Receptor beta (CD122) on memory T cells, as well as increasing IL-2 producers on re-infection." (PMID 22039531, 2011).
infection (continued). "From these results we concluded that virus specific CD4+T regulatory cells are generated during Chandipura virus infection in mice and these cells might control the activated lymphocytes during infection by different mechanism." (PMID 21612593, 2011). "Thus, memory CD8 T cells generated in the absence of RANTES were fully functional, responded efficiently to local infection rechallenge and showed evidence of having received CD4 T cell help during priming." (PMID 21814510, 2011). "In studies of infection by Fasciola hepatica and S. mansoni, the secreted antioxidant, peroxiredoxin (Prx), was shown to induce Ym1-expressing AAMs, which enhanced the secretion of IL-4, IL-5 and IL-13 from naïve CD4+T cells." (PMID 21246055, 2011). "Since we observed heightened bioactive TGFβ1 from mLN cells and within the colon at the chronic phase of infection, we speculate that TGFβ1 might have a role in the induction of gut-homing CD4+FoxP3+Tregs from naïve precursors." (PMID 21858239, 2011). "Interestingly, we observed that the numbers of CD4+ T cells were slightly reduced with the STM-WT infection." (PMID 21347426, 2011). "Our analysis demonstrates that the pDCs were more prone to apoptosis after infection during the acute phase of SIVmac239 infection, which may be due to their high expressions of CD4 and CCR5." (PMID 22174949, 2011). "The pathological consequences of infection of naïve CD4+ T cells may be dramatic, resulting in the depletion of the largest pool of CD4+ T cells in the body." (PMID 21284904, 2011). "A pronounced increase in the proportion of CD4+FoxP3+Tregs within colonic granulomas at the chronic phase of infection, from 2.9±0.6% to 18.8±0.7% was revealed by enumeration of double positive versus single positive cells in anti-CD4 / anti-FoxP3 immunostained cryosections of colonic tissue." (PMID 21858239, 2011). "Another study examined protein abundance changes in a CD4 cell line 36 hours post-infection, whereas the most recent study reports on global protein level changes in primary CD4 cells isolated from five donors, profiling proteomic changes post infection in a time-dependent fashion." (PMID 21777475, 2011). "Early infection and destruction of intestinal CD4+ T cells appears to be selective for memory CD4+ T cells co-expressing CD69, which are likely much more susceptible to infection through expression of appropriate co-receptors (CCR5) and their increased state of activation." (PMID 22096538, 2011). "ART use and low CD4 cell count have been associated with misclassification of individuals with non-recent infection as recently infected using serologic HIV incidence assays." (PMID 22073290, 2011). "The challenge viruses used in these assays were selected for growth in CrFK cells and, during this process of CrFK-adaptation, viruses were adapted to CD134-independent infection mediated by a direct interaction with CXCR4 (analogous to CD4-independent infection with HIV)." (PMID 22069520, 2011). "Taken together, the data presented in this manuscript and from previously published studies strongly suggest that CD4 T cells play a critical role in coordinating the anti-VZV/SVV response during primary infection that goes beyond providing help for CD8 and B cells." (PMID 22102814, 2011). "In contrast, after infection of CD4+ HeLa cells, it was observed that while the prevention of premature reverse transcription in the NC mutants resulted in lower quantities of initial reverse transcripts, the kinetics of reverse transcription were not restored to that of untreated wild-type HIV-1." (PMID 21682883, 2011). "However, almost all pDCs expressed CD4 and CCR5, which seem to imply that the pDCs were more susceptible to SIVmac239 infection than CD1c+ mDCs." (PMID 22174949, 2011). "Indeed, in agreement with published data, the relative number of CD4+ central memory cells (as a portion of naïve CD4+ cells) at day 10 post infection dropped 60%." (PMID 22043290, 2011).
infection (continued). "Thus, the non-conventional CD4+ T cell population also duplicates during a week of infection but it represents only 10% of spleen CD4+ T cells of which 40% are iNKT cells." (PMID 21814579, 2011). "The presence of BALT is indicative of an immune response in mice but is not specific as it has been associated with either CD4 or CD8 cell recruitment in rodent models of infection." (PMID 22039448, 2011). "The hypothesis was formulated that when HIV virions were incubated in increasing concentrations of soluble CD4 they reached a critical condition in terms of the number of gp120 molecules available for infection." (PMID 22216149, 2011). "We then addressed the question of whether or not the control of SIVagm.sab infection in RMs is due to a particular biology of the virus that may restrict infection to particular CD4+ T cell subsets." (PMID 21829366, 2011). "Successful and productive de novo virus production in DCs may also lead to cis-infection of CD4+ T-lymphocytes." (PMID 20934454, 2011). "Our study population, in contrast, consists of HIV patients with a probably slightly longer history of infection (1.30±1.75 years since diagnosis) with a mean age of 35.4 years, a mean baseline CD4+ T-cell count of 483 cells/μl and amongst females predominantly multigravidae." (PMID 21886779, 2011). "One recent study found that mice provided with CD4+TCR-transgenic effector T cells specific for the M. tuberculosisantigen ESAT-6 prior to infection can restrict bacterial population size to a lowerlevel but cannot prevent establishment of infection." (PMID 21637811, 2011). "Whether or not functional differences in terms of both stimulatory and regulatory properties occur between CD4+ and CD4− cDC during stressful conditions (i.e. in the context of infection) is unknown at present." (PMID 22066016, 2011). "Chandipura virus specific CD4+ T regulatory cells induced during infection." (PMID 21612593, 2011). "In conclusion, the specific affinity of gp120 for α4β7 may play a critical role in the infection of CD4+ T cells in mucosal tissues." (PMID 21284901, 2011). "Thus, viruses in BR24 are evolving early to adopt an “open” Env conformation in order to bind CD4 more efficiently for infection of CD4low cells." (PMID 21760891, 2011). "We hypothesized that M. tuberculosis evades adaptive immunity bymodulating the activation of CD4+ effector T cells at the siteof infection in the lungs." (PMID 21637811, 2011). "Despite the lack of season of birth effects on thymic output, lower CD4+ as well as CD3+ counts were associated with hungry/high infection season births." (PMID 21676219, 2011). "However, during infection of HeLa CD4+ cells, we did see that the NCH23C mutant still showed poor reverse transcription profiles with apparently unstable reverse transcripts after RTI treatment." (PMID 21682883, 2011). "Infection frequencies of other mucosal lymphoid sites could be similar to those in blood (0.01–1% CD4+ T cells)." (PMID 21994747, 2011). "When treated with APS (200 μg/ml) for 24 h ex vivo, the intranuclear Foxp3 protein, Foxp3 mRNA expressions and IL-10 secretion of CD4+CD25+Tregs isolated from burn plus infection mice on PBD 3 and 7 were obviously lower than those in untreated burn plus infection mice on PBD 3 and 7 (P<0.05)." (PMID 21698274, 2011). "Interestingly based upon lesion development, the DNA-TRYP(Pam3CSK4)+MVA-TRYP immunized mice depleted of CD4 T cells are significantly resistant to infection." (PMID 21695103, 2011). "However, many studies have shown that the loss and qualitative impairment of HIV-specific T-cell help occurs very early in infection and cannot therefore be predicted by the overall numbers of circulating CD4+ T-cells." (PMID 21359149, 2011). "CD4+ helper T cells are critical orchestrators of immune responses to infection and vaccination." (PMID 21245909, 2011).